BAX (BCL2 associated X, apoptosis regulator)
Diseases named in the same sentence as BAX in open-access papers (continued):
Sharing a sentence is not in itself a finding about the gene and the disease.
tumor (continued). "After the test, it was found that DNMT1 and HDAC1/2 in the tumor tissue were significantly downregulated, while the transcriptional levels of pro-apoptotic genes such as BAX, BNIP3, and APAF1 were significantly increased, and the tumor volume was significantly reduced." (PMID 41335282, 2025). "With the increaseof these ceramide species in serum, the BAX/BCL2 ratio increases in tumour tissue." (PMID 40821650, 2025). "Furthermore, when compared to the CHMm+NK group, the CHMm+RNK group displayed a significant increase in the positive rates of Caspase 3 and BAX cells in tumor tissue, along with a significant decrease in the positive rates of BCL-2 and GPX4." (PMID 38891683, 2024). "Of note, splice‐switching ASOs targeting BAX exhibited effective anti‐tumor activity." (PMID 38342602, 2024). "The increase in BAX/BCL-2 ratio reflected the critical confirmation of tumor cell death." (PMID 38499634, 2024). "Previous studies have shown that adaptation of tumor cells to VEN is characterized by different mechanisms resulting in functional loss of pro-apoptotic regulators like BAD, BAX, NOXA and PUMA or by a shift in dependency from BCL-2 to other anti-apoptotic proteins like MCL-1." (PMID 38961053, 2024). "Moreover, the relationship between BAX and immune infiltration and gene alteration was studied by the Tumor Immune Estimation Resource (TIMER) and cBioPortal tools." (PMID 39074253, 2024). "By diminishing the level of cyclin B1 and regulating the phosphorylation of protein kinase Chk1 and p21, the level of Bcl-2 was significantly reduced, and the BAX, cytoplasmic Cytochrome-C (Cyt c), Caspase-9 and Caspase-3 levels were increased to produce an anti-tumor effect." (PMID 38675663, 2024). "VDAC2 has been shown to promote cell apoptosis and limit tumor development through BAX." (PMID 38881325, 2024). "Interestingly, the mRNA level of the BCL-2 gene in the tumor sample injected with native CIMVs was increased by 1.4 (n = 5, **** p < 0.0001), while the mRNA level of the BAX gene remained unchanged, the BAX/BCL-2 ratio was 0.7." (PMID 36661524, 2023). "The BAX gene is involved in tumor suppression due to its role in promoting programmed cell death." (PMID 38003498, 2023). "In addition, the phosphorylation levels of p-AKT and BAX in tumor tissues were detected using an immunofluorescence assay." (PMID 36900408, 2023). "Mechanistic studies reveal that Fe-CDs can selectively promote tumor cell apoptosis through regulating PARP/Caspase 3/Caspase 9/BAX proteins, and activate antitumoral macrophages by inhibiting the IL-10/Arg-1 axis, which contributed to the superior anti-tumor performance of Fe-CDs." (PMID 37978538, 2023). "The as-synthesized Fe-CDs could selectively induce tumor cells apoptosis by BAX/Caspase 9/Caspase 3/PARP signal pathways and activate antitumoral macrophages by inhibiting the IL-10/Arg-1 axis, contributing to its significant tumor immunotherapy effect." (PMID 37978538, 2023). "HA-PEG-NHA-ZOL NP could increase the expression level of Bcl-2-associated X protein (BAX), indicating that HA-PG-NHA-ZOL NP could promote apoptosis in tumor cells." (PMID 37670948, 2023).
tumor (continued). "Furthermore, the expression of the pro-apoptotic protein BAX was significantly increased in tumor tissues in response to the probiotic powder." (PMID 36913356, 2023). "As a pro-apoptotic protein, BAX is involved in tumor progression and drug resistance." (PMID 37547766, 2023). "Additionally, proapoptotic genes like BAX lose their ability to act as tumor suppressors due to overexpression of BCL2." (PMID 37396945, 2023). "The administration of DM extract enhanced the staining of BAX in tumor and peritumoral areas." (PMID 36313224, 2022). "Additionally, some IRGs with copy number amplification (HMGB1, IL17RA, and BAX) showed increased expression in tumor tissues, while some IRGs with copy number deletions (IL10, NT5E, and ENTPD1) showed decreased expression in tumor tissues." (PMID 36386817, 2022). "Interestingly, ABT-263 was previously reported to exert its senolytic activity via the disruption of the BAX/BCL-xL complex in tumor cells." (PMID 35805077, 2022). "The BAX/BCL2 ratio was also considered one of the prognostic markers for tumor location in CRC." (PMID 35269511, 2022). "Basic research showed that quercetin could trigger BCL2/BAX-mediated apoptosis, necrosis, and mitotic mutation, and inhibit the migration potential of A549 cells, showing good anti-NSCLC tumor activity." (PMID 36523419, 2022). "Tumor cell apoptosis was next evaluated by checking cell surface annexin-v and BAX expression." (PMID 34488792, 2021). "In addition, Rh favourably inhibited tumours by activating the secretion of apoptosis-related proteins, such as caspase-3, BCL-2 and BAX, in tumour cells after treatment." (PMID 33632266, 2021). "The expression of BAX was higher in 517 tumor samples than 59 normal samples (P=0.0037)." (PMID 33390811, 2021). "Importantly, we found that the anti-tumour functions achieved by MCL-1 deletion or inhibition were completely dependent on pro-apoptotic BAX/BAK." (PMID 33785871, 2021). "Through the TIMER database 48, 49, we explored the BAX may effect tumor-infiltrating immune cells (B cell, CD8+ T cell, CD4+ T cell, macrophage, neutrophil, and dendritic cell)." (PMID 33390811, 2021). "Indeed, we also demonstrated an elevated number of damaged tumor cells with nuclear cleaved Caspase-3 positivity in both Capan1 and Panc1 cells after treatments, and the upregulation of BAX protein in mEHT treated Panc1 cells." (PMID 34955688, 2021).
tumor (continued). "Strikingly, in tumours that had been engineered for BAX/BAK deficiency, S63845 treatment had no impact on tumour growth." (PMID 33785871, 2021). "While the expression level of BAX was the highest in the tumor administration group." (PMID 34830310, 2021). "The selection yields in a BAX localization shift typically of about 2 log scales to the cytosol, regardless of the apoptosis predisposition in non-tumor cells and BAK regulation." (PMID 32486514, 2020). "Together, we discover a previously unrecognized link between cellular BAX localization and apoptosis resistance that characterizes a differential mechanism of malignant transformation in affected patients and links adverse tumor biology to high genetic instability and poor outcome." (PMID 32486514, 2020). "Previous studies demonstrated that S63845 could kill effectively Mcl-1 dependent tumor cells in a BAX-BAK-dependent fashion." (PMID 33362794, 2020). "BAX is a pro-oncoprotein that promotes tumor cell death when upregulated in the tumor cells." (PMID 32679837, 2020). "Therefore, HUH7 cells reflect BAX-protected tumor cells, whereas Hep3B cells and HCC68 cells show characteristics of non-protected tumor cells." (PMID 32486514, 2020). "Thus, protection against BAX-dependent apoptosis is characteristic for a subclass of patients with adverse tumor features and poor clinical outcome." (PMID 32486514, 2020). "Thus, this is the first report demonstrating that TMC inhibits tumor initiation and progression by modulating the miR-374a/BAX axis in TNBC." (PMID 32296334, 2020). "The significant expression of TIMP-1 and CINC-1 cytokines in co-culture media of K562 cell and BMSCs suggests that these cytokines could be involved in the inhibition of the tumor cell proliferation via BAX and caspase-3 cascade." (PMID 31009502, 2019). "BAX mRNA was found to synthesize BAX protein, which inhibits tumor growth by apoptosis." (PMID 31652668, 2019). "Inactivation of BAX might be a mechanism to escape cell death, providing a survival advantage to the tumor." (PMID 31570105, 2019). "For instance, dysfunction of BAX may further the tumor genesis of cells; thus, many chemotherapies try to indirectly intervene in this process." (PMID 30686270, 2019). "The fact that 3 patients carrying this mutation are positive for portal vein infiltration might support the role of BAX in tumor invasion and the possible inefficacy of sorafenib in these patients." (PMID 31570105, 2019). "Thus, immunohistochemistry (IHC) investigation demonstrated that ECPU-0001 treatment clearly reduced expression of BCL-2 and BCL-2-xL, while enhanced expression of BAX in tumor." (PMID 31450709, 2019). "The lowest Bcl-2/BAX ratio was detected for control samples and the highest for tumour samples." (PMID 29515335, 2018). "Since the intrinsic apoptotic pathway is an important barrier to tumorigenesis, we hypothesized that the impairment of BAX-mediated apoptosis by deletion of Vdac2, when combined with Bak deletion, should accelerate tumor development." (PMID 30478310, 2018). "Importantly, S55746 induces the critical hallmarks of the mitochondrial apoptosis pathway and kills BCL-2 dependent tumor cells in a BAX/BAK dependent manner." (PMID 29732004, 2018). "For this purpose, we analysed several apoptotic markers, such as the cleavage of caspases 3, 8 and 9, the cleavage of PARP, and the expression of the pro-apoptotic protein BAX after 72 h of amino acid restriction in several tumour cell lines, by western blot and by immunofluorescence." (PMID 28112156, 2017).
tumor (continued). "In vivo animal experiments confirmed that depletion of BAX promotes tumor growth." (PMID 28556798, 2017). "Altered expression of several biomarkers including increased expression of activated AKT, p21 and cyclin D1 and reduced expression of pro-apoptotic marker BAX was observed in the tumor adjacent normal (TAN) skin of acute ultraviolet B treated trigenic RXRαep−/− mice." (PMID 29121869, 2017). "Analysis of tumor tissue extracts by western blot analysis showed increased levels of proapoptotic protein, BAX, decreased p-BAD, and increased levels of cleaved caspase 3 and PARP in tumor tissues obtained from mice treated with Ad.EPCR compared to mice treated with PBS or Ad.Con." (PMID 27833109, 2016). "Exogenous STAT3 and CDDP may synergistically inhibit the xenograft tumour growth through up-regulation of BAX protein via GRP78." (PMID 27129294, 2016). "In contrast, sar@LIP induced the up-regulation of a broad spectrum of genes related to the positive induction of cell proliferation (CCND1, E2F3, PDGFRB and TEGT, a described BAX inhibitor), which corresponds to the tumor growth enhancement observed in vivo after sar@LIP administration." (PMID 27646588, 2016). "We first tested the transcription levels of Bcl-2, Survivin, and BAX in the tumor tissues." (PMID 27248325, 2016). "Additionally, a marked increase of BAX expression levels in SLMP53-1-treated tumor tissues, compared to vehicle, was observed." (PMID 26735173, 2016). "Our results showed that enforced expression of miR-128 inhibited the HNSCC cell proliferation and tumor xenograft growth by mediating the expression of BMI-1, BAG-2, BAX, H3f3b, and Paip2 mRNAs, suggesting that miR-128 might act as a tumor suppressor." (PMID 25764126, 2015). "In addition to SP1, tumor supporters such as E2F3a, BAX, BMI-1, DCX and Reelin are also targeted by miR-128." (PMID 24959930, 2014). "BAX mRNA expression status was associated with low tumor extent, negative regional lymph node status, and absence of distant metastases." (PMID 23777485, 2013). "Tumor cell proliferation was inhibited by the increased expression of cyclin-dependent kinase inhibitor 1 (p21/WAF1; Cdkn1A), and the apoptosis was induced by the activated expression of the Bcl-2–associated X protein (BAX)." (PMID 23840792, 2013). "In line with the comparable effects on tumor growth and final tumor weights, 17-AAG treatment caused very similar decreases in the Ki67 staining for both HCT116 BAX+/− and HCT116 BAX−/− xenografts as determined on day five following daily i.p doses of 80mg/kg of the HSP90 inhibitor." (PMID 24185264, 2013). "Our result showed that MSI-high tumors were associated with indolent tumor behavior regardless of TGFBR2 or BAX mononucleotide mutation status, independent of CIMP and other key tumor molecular biomarkers." (PMID 21949851, 2011). "Selected CRC target genes involved in apoptosis (BAX), tumor growth (TGFβRII), WNT pathway (AXIN2, TCF4, WISP3), DNA repair (ATM, ATR, BLM, BRCA1, BRCA2, DNAPKcs, MBD4, MRE11, MSH3, MSH6, RAD50, XRCC2) and PI3-kinase signaling (PTEN) were analyzed for mutations in MSI-positive HGG samples." (PMID 21637783, 2011). "In contrast to other tumour parameters and treatment arm, a significant association of G category and BSI was detected with tumours of lower differentiation showing a decreased level of BAX protein expression (P=0.01)." (PMID 17426704, 2007). "However, tumor cells demonstrate a remarkable ability to evade apoptosis through various mechanisms, including the upregulation of anti-apoptotic proteins within the Bcl-2 family and the downregulation of pro-apoptotic proteins, such as BAX and BAK." (PMID 40331942, 2025). "Moreover, DFFB deletion in tumor cells may attenuate killing by granzymes, as inactive DFFB is cleaved and activated by granzymes B and M. BAD/BAX deletions in tumor cells may also blunt rapid killing by granzyme B, which activates BAX and caspase-3." (PMID 41175874, 2025).
tumor (continued). "Therefore, we hypothesize that ZDHHC12 might modify BAX palmitoylation to control tumor cell death, thereby affecting tumor cell proliferation." (PMID 38177255, 2024). "Therefore, it is assumed that resistance to apoptosis mediated by BAX may be one of the mechanisms involved in pituitary tumorigenesis since this gene acts as an effector of apoptosis in several neoplasms." (PMID 39449743, 2024). "Importantly, BAX was widely reported due to its remarkable role in tumor progression and therapy." (PMID 39074253, 2024). "In addition, with the prolonged treatment of HepG2 cells with 20 μg/mL of the CXCL14 protein, the expression levels of pro-apoptotic genes BAK and BAX increased significantly, while the expression levels of tumor pro-proliferation genes HIF1A, mTOR and CDK1 decreased significantly." (PMID 37835641, 2023). "Furthermore, apoptotic BAX expression was examined in tumor cells." (PMID 37083240, 2023). "Therefore, an increased apoptotic predisposition prior tumorigenesis could result in selection towards a BAX-protected tumor." (PMID 32486514, 2020). "Genes involved in tumor suppression (e.g., TGFBR2), cell proliferation, DNA repair (e.g., MSH3, MSH6), and apoptosis (e.g., BAX) contain these repetitive sequences in the coding regions, where alterations tend to develop." (PMID 41214301, 2026). "Some genes containing these repetitive sequences code for proteins involved in tumor suppression (e.g., TGFBR2), cellular proliferation, DNA repair (e.g., MSH3, MSH6), and apoptosis (e.g., BAX)." (PMID 41214301, 2026). "The inhibition of the pro-apoptotic proteins BAX and BAD by elevated BCL3 expression leads to tumour cell survival and suppressed cytotoxic immune responses." (PMID 40486320, 2025). "To elucidate the relationship between classical apoptosis and anoikis resistance, we examined the expression levels of key apoptosis markers (e.g., BAX, BCL2, CASP3) between tumor and normal tissues, as well as between the C1 and C2 subtypes." (PMID 40861804, 2025). "By displacing proapoptotic proteins (e.g., BIM) and enabling BAX/BAK activation, Ven triggers the intrinsic apoptosis pathway in tumor cell." (PMID 41584590, 2025). "The drug combination increases ROS in neutrophils, triggering NET formation (NETosis) and the release of cathepsin G (CTSG), which enters tumor cells via RAGE, cleaves 14-3-3ε, and activates BAX-dependent mitochondrial apoptosis." (PMID 40805288, 2025). "We found that, compared to normal tissues, BAX, CHMP2A, CHMPB, IL1A, IL1B, and VPS24 were more strongly expressed in the cytoplasm and nucleus of tumor tissues." (PMID 39744500, 2025). "This inhibition is accompanied by the modulation of pro- and anti-apoptotic proteins BAX and BCL-2, a reduction in MYCN mRNA expression, and a decrease in TNF-α secretion, suggesting a direct impact on tumor growth and cell survival." (PMID 40942095, 2025).